ENSG00000304590 (novel transcript)
Gene: Long non-coding RNA gene on chromosome 7 (12,711,730 to 12,741,268, forward strand). Ensembl gene ENSG00000304590.
Gene Ontology:
Biological process: SRP-dependent cotranslational protein targeting to membrane, signal sequence recognition
Cellular component: signal recognition particle, endoplasmic reticulum targeting